DLL4 (delta like canonical Notch ligand 4)
Diseases named in the same sentence as DLL4 in open-access papers (continued):
Sharing a sentence is not in itself a finding about the gene and the disease.
leukemia (6 papers, 2013 to 2022). A malignant (clonal) hematologic disorder, involving hematopoietic stem cells and characterized by the presence of primitive or atypical myeloid or lymphoid cells in the bone marrow and the blood. "Since DC activation of naïve T cells allows them to be primed with antigens, Dll4+ DCs loaded with leukemia-associated antigens may facilitate the selective expansion of leukemic cell-reactive T cells and specifically boost the anti-leukemia activity." (PMID 30774630, 2019). "Since we showed that DLL4-expressing T cells from Tg8 mice could cause T cell development in nude animals, it is tempting to speculate that, in the Tg8 mouse model, a situation similar to donor cell leukemia could be taking place." (PMID 24386421, 2013). "In contrast, removal of the spleen in a genetic mouse model of delta-like canonical Notch ligand 4 (DLL4)-driven T-ALL fully protects against leukemia development, indicating a crucial role of the spleen in DLL4-driven T-ALL." (PMID 36428753, 2022). "In contrast, Notch1 and Notch2 genes were un-methylated in any of the leukemia cell lines and normal controls, while DLL1, DLL3, DLL4 and Hes6 showed only low levels of methylation (9–27%) in these leukemia cell lines." (PMID 23637910, 2013). "Additionally, the overexpression of Dll4 in a leukemia cell line led to increased protein expression of Myc." (PMID 28086833, 2017). "Dll4 was expressed in the BM microenvironment of T-ALL patients and NOD-SCID mice bearing the T-ALL xenograft; Dll4 blockage impaired T-ALL growth in NOD-SCID mice and increased leukemia cell apoptosis." (PMID 33585446, 2020).
asthma (5 papers, 2013 to 2023). "Previous studies have reported that blocking Dll-4-Notch signaling in animal models of experimental autoimmune encephalomyelitis and asthma decreased both Th17 response and clinical symptoms severity." (PMID 33981487, 2021). "By using the murine allergic asthma model, we have shown that blockage of Jagged1 signaling mitigated Th2-dominated airway inflammation, whilst inhibition of DLL4 signaling aggravated the asthma phenotypes." (PMID 31319491, 2019). "In this aspect, pharmacological inhibition of Notch by using γ-secretase inhibitors and Notch-DLL4 signaling blockage by antibodies suppressed Th17 development and decreased asthma severity." (PMID 31319491, 2019). "We found that whilst Jagged1 inhibition mitigated Th2-dominated airway inflammation, blockage of DLL4 aggravated the Th2-mediated asthma phenotypes." (PMID 28262821, 2017). "In this study, we investigated the distinct role of Jagged1 vs DLL4 in allergic airway diseases by using the OVA-induced murine asthma model." (PMID 28262821, 2017). "In vivo, DLL4 blockage impaired Treg differentiation which plausibly resulted in exaggerated asthma phenotypes." (PMID 28262821, 2017). "The aggravated asthma phenotypes after DLL4 blockage suggest probable beneficial effects of DLL4 during allergic airway inflammation." (PMID 28262821, 2017). "The role of DLL4 in endogenous Treg induction was next envisaged in the murine asthma model." (PMID 28262821, 2017). "The discrepancy can partly be reconciled by the context-dependent operation characteristic that orchestrates the overall outcome of Notch signaling; i.e. Th1/Th17-mediated pathologies induced by DLL4 in these disease models vs Th2-skewed responses attributed to Jagged1 in our asthma model." (PMID 28262821, 2017). "In addition, these DCs induced the differentiation of IL-10- and IFN-γ-secreting T cells, and adoptive transfer of OVA-pulsed Dll4-pretreated DCs alleviated OVA-induced asthma in recipient mice." (PMID 23696838, 2013). "It is worth noting that DLL4 also promoted Th17 differentiation; however, in the murine asthma model, Treg-mediated immune regulation, as induced by DLL4, overcame Th17-mediated inflammation, which conceivably led to aggravated allergic phenotypes after DLL4 blockage." (PMID 28262821, 2017). "However, based on our current results thus far, the “counterbalancing” theory could not fully explain the seemingly paradoxical results on neutrophilic airway inflammation, as can be induced by DLL4-elicited IL-17, and the otherwise mitigated asthma phenotypes after Jagged1signaling blockage." (PMID 28262821, 2017).
breast tumor (5 papers, 2016 to 2023). "NSD3 directly interacted with EZH2 and RNA polymerase II to stimulate H3K36 methylation-dependent transcriptional activation of NOTCH receptor cleavage-associated genes (including Adam12, DLL4, and Notch3), thereby activating Notch signaling to promote breast tumor progression." (PMID 34615858, 2021). "The Wnt genes Lef-1 and Axin-2 in cooperation with the Notch ligands Dll-3 and Dll-4 were detected in an array of 34 breast neoplasms, indicating that a type of carcinogenesis is on the way." (PMID 30111989, 2018). "The connection between ligand blockage and potential therapeutic usage was inevitable, especially when evidence revealed overexpression of Jagged-1 and Dll-4 on breast tumor xenografts." (PMID 30111989, 2018). "The Dll-4 expression profile in lactating mammary gland was equivalent to breast neoplasm." (PMID 30111989, 2018).
melanoma (5 papers, 2018 to 2025). A malignant, usually aggressive tumor composed of atypical, neoplastic melanocytes. "The molecular and functional changes in LECs induced by melanoma cells are mediated by the Delta-like protein 4 (DLL4)/Notch3/WNT5B signaling axis." (PMID 41511312, 2025). "DLL4-Fc induced the expression of NOTCH3 mRNA in the metastatic melanoma cell lines WM852 and WM165, while DLL1 induced NOTCH3 only in WM165." (PMID 37971882, 2024). "We further found that Notch ligand DLL4, expressed in LECs, is a potent inducer among the tested ligands of Notch3 in melanoma cells." (PMID 37971882, 2024). "A bi-directional DLL4/Notch3/WNT5B-dependent signaling cascade underlies crosstalk between melanoma and lymphatic endothelial cells and promotes melanoma lymphatic metastasis." (PMID 37971882, 2024). "We found that melanoma cells induced metastasis-promoting molecular and functional changes in LECs mediated by the DLL4/Notch3/WNT5B signaling axis." (PMID 37971882, 2024). "We next addressed the ability of DLL4-Fc to increase melanoma invasion by embedding the ligand-activated melanoma cells in a cross-linked 3D fibrin matrix for 4 days." (PMID 37971882, 2024). "In addition to MCAM‐mediated interactions, also other signalling mechanisms have been described to mediate melanoma–endothelial crosstalk such as Dll4‐Notch3 signalling." (PMID 39945026, 2025). "Interestingly, the full-length Notch3 receptor level was also increased by DLL1-Fc and DLL4-Fc treatments, which together with the observed increase in the mRNA levels suggest that Notch3 is induced through an autoregulatory loop in the melanoma cells." (PMID 37971882, 2024). "Specifically, we show that DLL4, expressed on the LEC surface, activates Notch3 in melanoma cells, which in turn triggers WNT5B transcription and protein expression in melanoma cells." (PMID 37971882, 2024). "Here, we report that the DLL4/Notch3/WNT5B signaling axis induced upon melanoma cell and LEC interaction promotes melanoma metastasis via its effects on LEC phenotype and function." (PMID 37971882, 2024). "Notch ligand DLL4 is a potent inducer of Notch3 and WNT5B in melanoma." (PMID 37971882, 2024). "Finally, DLL4, a Notch ligand expressed in LECs, was identified as an upstream inducer of the Notch3/WNT5B axis in melanoma." (PMID 37971882, 2024). "In addition, DLL4 was recently identified as a an upstream inducer of the Notch3/WNT5B axis mediating bidirectional prometastatic crosstalk between melanoma and lymphatic endothelial cells." (PMID 39951484, 2025).
renal cell carcinoma (5 papers, 2009 to 2021). "Multivariate logistic analysis of renal cell carcinoma (RCC) specimens showed that tumor hematogenous metastasis not only depended on angiogenesis but also was associated with tumor size and DLL4 density." (PMID 33198378, 2020). "Here we showed that DLL4 was elevated in endothelium and Notch signaling was activated in renal cell carcinoma (RCC)." (PMID 24931473, 2014). "Accordingly, therapeutic targeting of Dll4 in the treatment of renal cell carcinoma may hold much promise." (PMID 25393540, 2014). "In renal cell carcinoma, UCA1 upregulates Delta-like 4 (DLL4) expression by acting as a ceRNA of miR-182-5p, and induces the EMT process via the DLL4-mediated Notch pathway, which in turn promotes cell proliferation and migration, and inhibits apoptosis." (PMID 33777227, 2021). "Given the cross-talk between the vascular endothelial growth factor (VEGF) and Delta-Notch pathways in tumor angiogenesis, we examined the activity of a function-blocking Dll4 antibody, REGN1035, alone and in combination with anti-VEGF therapy in renal cell carcinoma (RCC)." (PMID 25393540, 2014). "Normal kidney did not express Dll4, but endothelial cells in renal cell carcinoma showed endothelial expression of Dll4, consistent with previous in situ hybridisation results." (PMID 19844231, 2009).
small cell lung carcinoma (5 papers, 2016 to 2025). Small cell lung cancer (SCLC) is a highly aggressive malignant neoplasm, accounting for 10-15% of lung cancer cases, characterized byrapid growth, and early metastasis. "Another study proved that Dll4 antibodies were able to suppress tumor stem cells in a Small-cell lung cancer subpopulation promoting the importance of Dll4 antibodies in cancer treatment." (PMID 35406423, 2022). "Kuramoto and coworkers generated a soluble form of Dll4, called Dll4-Fc, which suppressed liver metastasis of small cell lung cancer (SCLC) cells expressing high levels of Dll4." (PMID 29462871, 2018).
breast adenocarcinoma (4 papers, 2013 to 2018). "Consistent with our finding that Notch4 is expressed in the tumor vasculature, the Notch ligand Dll4 is detected in the vessels of infiltrating human breast adenocarcinoma samples, making it a possible ligand for Notch4 in tumor vasculature." (PMID 23601498, 2013).
cervical cancer (4 papers, 2020 to 2026). A primary or metastatic malignant neoplasm involving the cervix. "Tumor angiogenesis driven by the VEGF/DLL4-Notch axis promotes cervical cancer progression, and the anti-VEGF antibody bevacizumab shows limited clinical benefit because of acquired resistance." (PMID 42093872, 2026). "In our present study, we further studied the effects of DLL4 on the biological behavior and radiosensitivity of cervical cancer cells." (PMID 32742191, 2020). "Downregulation of DLL4 inhibited the progression and increased the radiosensitivity in cervical cancer cells by reversing EMT." (PMID 32742191, 2020). "However, a prospective study involving a high number of patients is warranted to validate the role of DLL4 as a novel predictive biomarker for the responses of cervical cancer patients with CC who are receiving cCRT." (PMID 32742191, 2020). "Previously, we have found that high DLL4 expression in tumor cells may predict the pelvic lymph node metastasis and poor prognosis in patients with cervical cancer." (PMID 32742191, 2020). "We previously found that high DLL4 expression level in tumor cells may predict the pelvic lymph node metastasis and poor survival in patients with FIGO stages I–II cervical cancer." (PMID 32742191, 2020). "The expression of DLL4 and epithelial–mesenchymal transition (EMT) phenotype markers in cervical cancer cell lines or tissues were detected using Western blotting, and the expression of DLL4 mRNA in cervical cancer cell lines or tissues was detected using Quantitative real-time PCR." (PMID 32742191, 2020).
endometrial cancer (4 papers, 2015 to 2022). Primary or metastatic malignant neoplasm involving the endometrium (mucous membrane that lines the endometrial cavity). "Dll4 reveals a major key role in endometrial cancer formation while it seems to have a critical role in both tumor angiogenesis and cancer stem cells activation." (PMID 35406423, 2022). "In endometrial carcinoma, the expressions of Notch, Jagged1, and DLL4 are significantly increased and are related to the stage and prognosis of the disease, and blockage of the Notch signaling pathway significantly inhibits the growth and invasion of endometrial adenocarcinoma cells." (PMID 26307032, 2015).
myocardial infarction (4 papers, 2019 to 2025). Gross necrosis of the myocardium, as a result of interruption of the blood supply to the area, as in coronary thrombosis. "The study revealed an increase in Notch1 and DLL4 levels, particularly at the 24th hr and 7th day after the occurrence of myocardial infarction." (PMID 39850112, 2025).
non-small cell lung carcinoma (4 papers, 2013 to 2025). A group of at least three distinct histological types of lung cancer, including non-small cell squamous cell carcinoma, adenocarcinoma, and large cell carcinoma. "In this study, we analyzed correlations among VM, Notch4, DLL4, and KAI1/CD82 in non-small cell lung cancer (NSCLC), and their respective associations with patients’ clinicopathological parameters and survival rate in NSCLC." (PMID 30593175, 2018). "To evaluate the role of VEGF single nucleotide polymorphisms (SNPs), we examined the expression of several angiogenesis-related proteins [VEGF, hypoxia-inducible factor-1α (HIF-1α) and delta-like ligand 4 (Dll4)] and the spread of microvessels in resected non-small cell lung cancer (NSCLC)." (PMID 23064377, 2013). "The correlation between VM, or Notch4, or DLL4, or KAI1/CD82 and clinicopathological characteristics in non-small cell lung cancer." (PMID 30593175, 2018). "In a retrospective study titled “Evaluation of the correlation of vasculogenic mimicry, Notch4, DLL4, and KAI1/CD82 in the prediction of metastasis and prognosis of the course of non-small cell lung cancer” a cohort of 189 patients was analyzed to assess the impact of VM on OS." (PMID 40786517, 2025). "In the article “Evaluation of the correlation of vasculogenic mimicry, Notch4, DLL4, and KAI1/CD82 in the prediction of metastasis and prognosis in non-small cell lung cancer”, the structure presented as VM could be considered a blood lake." (PMID 40786517, 2025). "For the most investigated example, Demcizumab is a humanized anti-DLL4 IgG2 mAb, whose antitumor efficacy in combination with specific first-line antitumor drugs has been tested on PDAC and non-small cell lung cancer (NSCLC) respectively in various phase I/II trials." (PMID 34959397, 2021).
pulmonary hypertension (4 papers, 2021 to 2024). Increased pressure within the pulmonary circulation due to lung or heart disorder. "Inhibition of DLL4 has been associated with the development of pulmonary hypertension, but the mechanism is incompletely understood." (PMID 38791441, 2024). "Notably, anti-DLL4 monoclonal antibodies, developed to treat cancer, have been associated with pulmonary hypertension (PH) in clinical trials." (PMID 38791441, 2024). "Notably, anti-DLL4 monoclonal antibodies, developed to treat cancer, have been associated with the development of pulmonary hypertension (PH) in clinical trials." (PMID 38903104, 2024). "Lung biopsies from individuals with PAH have shown elevated amounts of JAG-1 protein and reduced levels of DLL-4 protein in pulmonary hypertensive lung tissue compared to normotensive lung specimens by Western blotting." (PMID 38892440, 2024). "This may provide a mechanistic explanation for the development of pulmonary hypertension in patients treated with monoclonal antibodies that block DLL4." (PMID 38903104, 2024). "While DLL4/NOTCH1 signaling appears to protect the pulmonary vasculature, how and under what conditions DLL4 loss or inhibition contributes to the development of pulmonary hypertension and pathologic vascular remodeling is not understood." (PMID 38791441, 2024). "Conversely, DLL4/NICD activation by olmesartan, an angiotensin II receptor blocker, attenuated transverse aortic constriction-induced cardiac remodeling in mice and monocrotaline-induced pulmonary hypertension and right ventricular hypertrophy in rats." (PMID 38791441, 2024).
triple-negative breast carcinoma (4 papers, 2019 to 2025). An invasive breast carcinoma which is negative for expression of estrogen receptor (ER), progesterone receptor (PR), and human epidermal growth factor receptor 2 (HER2). "To summarize, based on our recent study, we investigated the impact of genetically heterogeneous notch-Dll4 inheritance on the contrast agent uptake and clearance in triple-negative breast cancer xenografts." (PMID 36900252, 2023). "Compared with SSIL2Rγ- tumors, the density of DLL4-positive blood vessels decreased by 60% in triple negative breast cancer implanted in SS.BN3IL2Rγ- rats." (PMID 32373218, 2020). "The eventual results of this study may help physicians decide if a given triple-negative breast cancer patient will benefit from a Dll4 targeted therapy." (PMID 36900252, 2023).
cerebral cavernous malformation (3 papers, 2013 to 2024). A disorder characterized by malformations in the structure of the capillaries in the brain. "Similarly, expression of the arterial protein DLL4 was observed in the endothelium in mouse models of cerebral cavernous malformation (CCM), a VM of the brain." (PMID 34043714, 2021).
clear cell renal cell carcinoma (3 papers, 2013 to 2022). "Multiple studies have shown that the expression of Notch-related ligand DLL4 is elevated in surgical specimens of renal clear cell carcinoma and is an independent prognostic factor." (PMID 35096263, 2022). "Delta-like ligand 4 (Dll4)-Notch signaling is important in tumor angiogenesis; however, the prognostic value of D114 detection in patients with clear cell renal cell carcinoma (CCRCC) remains unclear." (PMID 25364440, 2014). "However, the regulation of DLL4 in clear cell renal cell carcinoma (ccRCC) has not yet been systematically elucidated." (PMID 23826258, 2013).
diabetic macular edema (3 papers, 2021 to 2023). "Activation of the Notch pathway induces vessel leakage in murine retinas, and some of the Notch ligands (delta-like ligand 4 (DLL4) and Jagged1) are elevated in patients with diabetic macular edema." (PMID 37047375, 2023). "Thirdly, we did not check the relationship between the level of DLL4 and diabetic macular edema." (PMID 34362349, 2021).
diabetic retinopathy (3 papers, 2021 to 2022). "In addition, a study has shown that the DLL4-NOTCH 1 pathway aggravates vascular permeability in diabetic retinopathy." (PMID 36465455, 2022).
fibrosarcoma (3 papers, 2014 to 2022). A malignant mesenchymal fibroblastic neoplasm affecting the soft tissue and bone. "Administration of recombinant Dll4-Fc or anti-Dll4 polyclonal antibody in an HT1080-RM (generated from a bevacizumab-resistant human fibrosarcoma) tumor model caused an increase in vessel density and smaller tumors volumes." (PMID 25601901, 2014). "A rise in vessel density and reduced tumor dimension were observed after the administration of recombinant Dll4-Fc or anti-Dll4 polyclonal antibody in a bevacizumab-resistant human fibrosarcoma tumor model." (PMID 36627893, 2022).
Hypertension (3 papers, 2021 to 2024). The presence of chronic increased pressure in the systemic arterial system. "A Phase I trial of Regeneron‘s anti-DLL4 antibody Enoticumab in patients with solid tumors showed some evidence of disease stabilization in a subset of patients but also resulted in cardiotoxicity and hypertension, which may reflect the role of DLL4/Notch in the vascular endothelium." (PMID 38672496, 2024).